FBXO8 (F-box protein 8)
Description:
May promote guanine-nucleotide exchange on an ARF. Promotes the activation of ARF through replacement of GDP with GTP (Potential).
Synonyms: FBS; FBX8; DC10
Tractability: PROTAC: ubiquitination databases record sites on it.
Gene: Protein-coding gene on chromosome 4 (174,236,658 to 174,283,676, reverse strand). Ensembl gene ENSG00000164117.
Subcellular location (Human Protein Atlas): Nucleoplasm; Cytosol
Gene Ontology:
Molecular function: protein binding; guanyl-nucleotide exchange factor activity
Biological process: SCF-dependent proteasomal ubiquitin-dependent protein catabolic process; ubiquitin-dependent protein catabolic process; regulation of ARF protein signal transduction
Cellular component: SCF ubiquitin ligase complex; ubiquitin ligase complex
Genetic constraint (gnomAD): Loss-of-function variants: 11 observed, 26.19 expected, observed/expected ratio (o/e) 0.42, 90% interval 0.26 to 0.69. The upper end of that interval is the gene's LOEUF score, 0.69, which puts it in group 2 of 6, group 1 being the genes least tolerant of losing a copy. Missense variants: 245 observed, 344.05 expected, observed/expected ratio (o/e) 0.71, 90% interval 0.64 to 0.79. Synonymous variants: 119 observed, 119.45 expected, observed/expected ratio (o/e) 1, 90% interval 0.86 to 1.16.
Homologues: Orthologues: chimpanzee FBXO8 (100% identical), macaque FBXO8 (99% identical), rabbit FBXO8 (99% identical), pig FBXO8 (99% identical), dog FBXO8 (98% identical), guinea pig FBXO8 (97% identical), mouse Fbxo8 (96% identical), rat Fbxo8 (96% identical), tropical clawed frog fbxo8 (82% identical), zebrafish fbxo8 (81% identical), Caenorhabditis elegans mon-2 (11% identical). Paralogues in human: ARFGEF1 (29% identical), ARFGEF2 (26% identical), IQSEC1 (25% identical), IQSEC2 (25% identical), GBF1 (24% identical), CYTH2 (24% identical), CYTH1 (24% identical), CYTH3 (24% identical), IQSEC3 (24% identical), CYTH4 (23% identical), MON2 (18% identical), PSD4 (15% identical), and 3 more.
Diseases named in the same sentence as FBXO8 in open-access papers:
FBXO8 is named in the same sentence as 29 diseases in open-access papers, as found by Europe PMC text mining. Sharing a sentence is not in itself a finding about the gene and the disease. The quoted sentences say what the papers report.
colorectal cancer (8 papers, 2019 to 2025). A primary or metastatic malignant neoplasm that affects the colon or rectum. "Downregulation of FBXO8 expression has been observed in liver cancer, gastric cancer, renal cancer and colorectal cancer, with its reduced expression closely associated with poor patient prognosis." (PMID 40375984, 2025). "Mechanistically, one study have identified GSTP1 as a substrate of FBXO8-mediated ubiquitination, which suppresses malignant behaviors in colorectal cancer." (PMID 40375984, 2025).
tumor (8 papers, 2013 to 2025). "Knockdown of FBXO8 promotes tumor progression and inhibits apoptosis, underscoring its potential for therapeutic applications." (PMID 40375984, 2025). "In FBXO8-knockdown mouse models, in vivo investigations demonstrated increased tumor growth, reduced apoptosis, and diminished survival rates." (PMID 40375984, 2025). "Knockdown of FBXO8 led to the suppression of apoptosis and increased tumor growth, suggesting potential therapeutic applications." (PMID 40375984, 2025). "Although research on FBXO8 in solid tumors and hematological malignancies is still in its early stages, evidence suggests it plays a potential role in tumor initiation and progression." (PMID 40375984, 2025). "It was worth mentioning that FBXO family members FBXO8, FBXO13, and FBXO34 were linked to tumor staging, and FBXO50 had an associated trend with tumor staging." (PMID 35046938, 2021).
cancer (5 papers, 2013 to 2025). A tumor composed of atypical neoplastic, often pleomorphic cells that invade other tissues. "Although fewer research have been conducted on different cancers, FBXO8 generally suppresses tumors through a variety of methods." (PMID 40375984, 2025).
digestive system tumors (1 paper, 2025). "Current studies on FBXO8 in digestive system tumors indicate its predominantly protective role." (PMID 40375984, 2025).
FBXO8 also shares sentences with these, for which no sentence is quoted: asthma (4 papers); breast carcinoma (4); allergic disease (2); Autoimmunity (2); colon cancer (2); adenoma (1); carcinoma in situ (1); celiac disease (1); Cirrhosis (1); colitis (1); gastric cancer (1); glioma (1); hepatocellular carcinoma (1); infection (1); Intellectual disability (1); liver cancer (1); lung carcinoma (1); lymph node metastasis (1); melanoma (1); multiple sclerosis (1); Portal vein thrombosis (1); psychiatric disorder (1); renal carcinoma (1); renal clear cell carcinoma (1); Type 1 diabetes (1).